DHX9 (DExH-box helicase 9)
Diseases named in the same sentence as DHX9 in open-access papers (continued):
Sharing a sentence is not in itself a finding about the gene and the disease.
cancer (continued). "Active screening for DHX9 inhibitors is in progress, as they can potentially be used as therapeutic agents specifically attacking cancer cells." (PMID 36761420, 2022). "DHX9 is overexpressed in lung cancer and its suppression is selectively lethal to cancer cells, but is tolerable for normal cells." (PMID 36761420, 2022). "The TMA was stained with DHX9, and the DHX9 was mainly detected on the nuclear cancer cells and partly in the cytoplasm." (PMID 36578944, 2022). "Analysis of a public dataset reporting expression data from PC (n = 47) and benign prostate (n = 48) samples (GSE29079) indicated that DHX9 expression levels were significantly higher (p value = 7.00 e− 03) in PC samples compared to non-cancer samples." (PMID 35590370, 2022). "In conclusion, our study demonstrates a novel role for DHX9 in restricting oncolytic MYXV replication in human cancer cells." (PMID 33952639, 2021). "In this article, we demonstrate that DHX9 can form unique antiviral granules in the cytoplasm during myxoma virus (MYXV) replication in human cancer cells." (PMID 33952639, 2021). "In certain members of the cancer cell types tested, knockdown of endogenous levels of DHX9 using RNAi significantly enhanced MYXV replication." (PMID 33952639, 2021). "DHX9 was identified as one of the antiviral RNA helicases for which targeted knockdown enhanced MYXV replication in multiple cancer cell types that are normally permissive, semipermissive, and nonpermissive to MYXV replication." (PMID 33952639, 2021). "Though it has been reported largely that DHX9 can function as a partner to regulate the expression of some gene or non‐coding RNA in cancer, the expression and key role of DHX9 itself in HCC remain to be studied further." (PMID 34676915, 2021). "Directed knockdown of DHX9 significantly enhanced viral late protein synthesis and progeny virus formation in normally restrictive cancer cells." (PMID 33952639, 2021). "The effect of DHX9 on cancers appears to be cell‐type specific, dependent on the kind of binding partners." (PMID 34676915, 2021). "When formed, DHX9 antiviral granules significantly reduced nascent protein synthesis in the MYXV-infected cancer cells." (PMID 33952639, 2021). "In order to understand the mechanisms how RNA helicases such as DHX9 restrict MYXV replication only in selective human cancer cells, we first studied the localization of DHX9 in virus-infected cells." (PMID 33952639, 2021). "DHX9 antiviral granules reduced viral protein synthesis in all the human cancer cell types we have tested, albeit at variable levels." (PMID 33952639, 2021). "DHX9′s multitude of functions in the development of cancer highlight a pivotal role in malignancy and the potential as both a biomarker and selective target for cancer therapy." (PMID 33804185, 2021). "Our review discusses the ascribed functions of DHX9 in cancer, explores its enigmatic nature and potential as an antineoplastic target." (PMID 33437516, 2020). "DHX9 activity has been identified as a factor in the transcription of both oncogenes and tumor suppressor genes in human cancers." (PMID 33437516, 2020). "For example, RNA helicase A/DHX9, as a potential therapeutic target, is associated with cancer risk and inflammation." (PMID 33490290, 2020). "It is clear from the literature cited above that DHX9 has well-defined roles as an oncogene and a tumor suppressor in different tissues and cancer cell types." (PMID 33437516, 2020). "This review focuses on the role of DHX9 in the development and progression of cancer, highlights DHX9 as a potential biomarker for the evaluation of cancer progression and discusses strategies for targeting DHX9 as novel therapeutic avenues for cancer therapy." (PMID 33437516, 2020).
cancer (continued). "The aptamer binds DHX9 with high affinity and specificity allowing preferential action in cancer cells over normal tissue due to DHX9 overexpression in CRC cells." (PMID 33437516, 2020). "DHX9 plays a fundamental role in mediating genomic stability as well as regulating cellular processes preceding the development of numerous cancer hallmarks." (PMID 33437516, 2020). "siRNA-mediated DHX9 knockdown enhanced MYXV replication in cancer cells, showing that DHX9’s regulatory role in the antiviral immune response is highly relevant in this context." (PMID 33437516, 2020). "Given that DHX9 is overexpressed in many cancers and contributes to the development of numerous hallmarks of cancer (as previously discussed), the helicase should represent an attractive antineoplastic target." (PMID 33437516, 2020). "Our discovery provides an alternative point of view that targeting DHX9 with differential molecular statuses will be critical when developing a strategy against DHX9 to tackle cancer." (PMID 32187976, 2020). "One method by which DHX9 activity has been shown to influence cancer cell invasion is via interactions with lncRNAs leading to modulation of their activity." (PMID 33437516, 2020). "In another study, DHX9 was identified as a host antiviral RNA helicase in human cancer cell lines where MYXV replicated poorly, for example, pancreatic cancer cell line PANC-1 and renal cancer cell line 786-0." (PMID 32456120, 2020). "The diverse implications of DHX9 in malignancy exposes the protein as a potential marker for cancer detection and intervention." (PMID 33437516, 2020). "While the literature franking the involvement of DHX9 in the development and progression of cancer is robust and plentiful, a newly discovered feature of DHX9 revolves around resistance to chemotherapeutic agents." (PMID 33437516, 2020). "Realization of DHX9’s pivotal role in the development of several hallmarks of cancer has boosted the enzyme's potential as a cancer biomarker and therapeutic target, opening up novel avenues for exploring DHX9 in precision medicine applications." (PMID 33437516, 2020). "In particular, irregular DHX9 activity is attributed to the development of several hallmarks of cancer, however, it can have both pro- and anti-cancer effects, thus leading to conflicting views on DHX9's role in cancer development." (PMID 33437516, 2020). "Using this approach, cellular DHX9 was identified as an additional cellular interaction of M029 in human cancer cells." (PMID 32456120, 2020). "Our review discusses the vast array of DHX9’s functions in cancer development, and its potential as a target for cancer treatment." (PMID 33437516, 2020). "DHX9 and other RNA/DNA hybrid-interacting helicases are overexpressed in cancers, highlighting their potential role in the cancer transcriptional program." (PMID 29742442, 2018). "That DHX36 and DHX9 are overexpressed in cancer tissues supports the proposed role of RNA helicases in tumor initiation, progression and maintenance." (PMID 30591072, 2018). "When comparing the expression levels of the helicases across normal tissue and tumors, recovered from the GENT database, we found that DHX36 displayed altered expression levels in eight and DHX9 in nine out of 15 types of cancers analyzed." (PMID 30591072, 2018). "DHX9 and other interactome helicases are overexpressed in cancer, linking R-loop-mediated DNA damage and disease." (PMID 29742442, 2018). "We found that multiple members of the DEAD/H helicase family, including DHX9, are strongly enriched in the RNA/DNA hybrid interactome and they are frequently deregulated in a range of cancers." (PMID 29742442, 2018). "Further exploration of the chemotherapeutic potential of targeting DHX9 has been carried out in other mouse and human cancer models." (PMID 28427210, 2017).
cancer (continued). "Due to the important regulatory role played by DHX9, there is growing evidence of its implications in human diseases such as various cancers and viral infections." (PMID 28427210, 2017). "This review will provide an overview of the structure, biochemistry, and biology of DHX9, its role in cancer and other human diseases, and the possibility of targeting DHX9 in chemotherapy." (PMID 27034008, 2016). "Given the importance of DHX9 in cancer cells resistance and proliferation, future work will investigate this issue." (PMID 26450900, 2015). "DHX9, mainly exerting oncogenic roles, is aberrantly expressed in several cancers." (PMID 40659605, 2025). "Given the accumulating evidence supporting the autophagy inhibitor-chloroquine (CQ) in tumor suppression and cancer therapy, and the preliminary validation of DHX9 inhibitor exerting anti-tumor effects, we wondered the combination effects of DHX9 silencing and CQ treatment." (PMID 40659605, 2025). "As such, depletion of DHX9 in many cancer cells induces viral mimicry." (PMID 39221819, 2024). "PARP1 and DHX9 are key players in genomic stability and cancer." (PMID 38247850, 2024). "YBX1 and DHX9 have been extensively studied in cancer research." (PMID 39558374, 2024). "Another key player in the suppression of dsRNA sensing in cancer is the DEAH-box helicase DHX9." (PMID 39221819, 2024). "Given the critical role of DHX9 SUMOylation in suppressing R-loops and the increased DNA damage in cells expressing DHX9K120R, we postulated that cancer cells with DHX9K120R might be more susceptible to genotoxic stress." (PMID 39019926, 2024). "Combined therapies targeting ADAR1 and DHX9 may serve as an effective means of treating breast and potentially other cancers by inducing viral mimicry." (PMID 38530197, 2024). "The phosphorylation level of DHX9 was also increased in cancers." (PMID 37214432, 2023). "Firstly, we profiled the pan cancer expression pattern of DHX9 based on the TGCA database." (PMID 37214432, 2023). "Therefore, DHX9 expression shared similar trends with both TMB and MSI values, which suggested that DHX9 was a promising biomarker to predict the efficacy of immunotherapy in cancers." (PMID 37214432, 2023). "The oncogenic roles of DHX9 in cancers were further verified by in vitro experiments." (PMID 37214432, 2023). "Studies have shown that some post-translation modifications of DHX9 occur in cancer or drug-resistant cells and may be therapeutic targets for cancer." (PMID 37214432, 2023). "In addition, DHX9 expression in most cancer types had an obvious positive correlation with several checkpoints, such as TGFBR1 (transforming growth factor-beta receptor 1), KDR (vascular endothelial growth factor receptor-2, VEGFR-2), and CD274 (PD-L1)." (PMID 37214432, 2023). "DHX9 was a potential biomarker to predict immunotherapy efficacy and a target for cancer treatment." (PMID 37214432, 2023). "This study integrated the pan-cancer analysis and in vitro and vivo experiments to characterize the role of DHX9 in various cancers, which would provide a better understanding of tumorigenesis and progression, and help to discover novel targets for cancer treatment." (PMID 37214432, 2023). "Because RPA and DHX9 are present in cancer cells throughout the cell cycle, expression of TUG1 via the ATR-CHK1 pathway may foster immediate interactions between these molecules in order to prevent overabundant R-loop accumulation specifically at S phase." (PMID 37607907, 2023). "However, the pan-cancer expression profile and prognostic significance of DHX9 remain uncharacterized." (PMID 37214432, 2023). "DExH-box helicase 9 (DHX9) plays a central role in many cellular processes but its expression pattern and prognostic value in most types of cancer remain unclear." (PMID 37214432, 2023).
cancer (continued). "Recently, DHX9 has been found to participate in the recruitment of BRCA1 to RNA and promote DNA end resection in homologous recombination, as well as prevent R-loop-associated DNA damage and be overexpressed in cancer." (PMID 35814441, 2022). "The DHX9 was mainly detected on the nuclear of cancer cells and partly in the cytoplasm." (PMID 36578944, 2022). "In this context, the effect of etoposide on DHX9 expression could be instrumental to hamper cancer cell proliferation and metastasis." (PMID 35326688, 2022). "Data from The Cancer Genome Atlas were mined to evaluate the potential role of DHX9 in PC." (PMID 35590370, 2022). "DHX9 is overexpressed in various types of cancers, including HCC, which is confirmed in our study." (PMID 34820372, 2021). "Since DHX9 antiviral granules reduced MYXV late protein synthesis in human cancer cells, we also checked whether transcription of MYXV-carrying genes is inhibited." (PMID 33952639, 2021). "Additionally, the subset of MYXV-restricted human cancer cells where the DHX9 pathway is fully active can be converted from a restrictive to a more MYXV-permissive phenotype by selectively inhibiting DHX9 or by blocking the signaling pathway." (PMID 33952639, 2021). "DHX9 antiviral granules reduce nascent protein synthesis in the MYXV-infected human cancer cells." (PMID 33952639, 2021). "It is reported that the knockdown of DHX9 can promote the migration of A549 cells, suggesting they may have a similarity in the role of mediating the migration of cancer cells through a shared functional domain." (PMID 33987090, 2021). "DHX9 regulates MYXV late stages of replication in all types of human cancer cells." (PMID 33952639, 2021). "We next studied the impact of DHX9 antiviral granules on MYXV replication in human cancer cells." (PMID 33952639, 2021). "Some studies suggested that DHX9 functioned as an oncogene and highly expressed in cancer tissues." (PMID 34676915, 2021). "Overall, given DHX9’s regulatory role in the life cycle of many viruses used as OVs, DHX9 could be targeted to enhance cancer cells’ response to OVs, thereby widening the applications of targeting DHX9 in cancer therapy to modulate cancer immunotherapy." (PMID 33437516, 2020). "DHX9’s multitude of functions in the development of numerous hallmarks of cancer highlight a pivotal role in malignancy and potential as both a biomarker and selective target for cancer therapy." (PMID 33437516, 2020). "It therefore appears that DHX9 may contribute to the overexpression of cyclin D1 in cancer following oncogenic EGFR upregulation, thus promoting proliferation and replicative immortality." (PMID 33437516, 2020). "DHX9 has been reported to be overexpressed in various types of malignant tumors and might be a potential therapeutic target for the treatment of NSCLC." (PMID 32983988, 2020). "Aberrant DHX9 activity leading to genomic instability and dysregulation of molecular events can have profound pathological consequences including malignant development, and it is clear that overexpression of DHX9 is a characteristic of many cancer types." (PMID 33437516, 2020). "DHX9 with multiple statuses regulated by posttranslational modifications may exert distinct functions in cancer cells and is worth further investigation." (PMID 32187976, 2020). "The expression of DHX9 was significantly associated with the abundance of infiltrating immune cells: B cells in 17 cancers, CD8+ T cells in 22 cancers, CD4+ T cells in 12 cancers, neutrophils in 31 cancers, macrophages and myeloid dendritic cells in 18 cancers." (PMID 37214432, 2023).
cancer (continued). "To better understand the mechanisms underlying the association of NUSAP1 overexpression and cancer aggressiveness, we used AP–MS to identify novel interactions between NUSAP1 and several proteins with described functions in R-loop biology and DDR, including DHX9, ILF2, HNRPC, FUS, and RBMX." (PMID 37047232, 2023). "However, memory and Th2 CD4+ T cells, mast cells, and common lymphoid progenitor were most positively associated with the DHX9 in these different cancers, while effector memory CD4+ T cells and NK T cells, macrophages, and monocytes were negatively associated with the expression of DHX9." (PMID 37214432, 2023). "In addition, DHX9 has been confirmed to be involved in DDR in other cancer types." (PMID 35814441, 2022). "Thus, DHX9 might also be required to support the higher transcriptional and metabolic activity of cancer cells by preventing R-loop accumulation." (PMID 35326688, 2022). "Thus, our study suggests that DHX9 has antiviral activity in human cancer cells, and this pathway can be targeted for enhanced activity of oncolytic poxviruses against even restrictive cancer cells." (PMID 33952639, 2021). "It would be interesting to test in the future whether these cellular factors or pathways are linked with the formation of DHX9 antiviral granules or operate independently to contribute to the nonpermissiveness in selected cancer cell types." (PMID 33952639, 2021). "Additionally, R-loop perturbations that occur in most cancers induce aberrant transcription of oncogenes and tumor suppressor genes, suggesting that DHX9’s function in R-loop resolution may be defective in cancer cells." (PMID 33437516, 2020). "Targeting DHX9 hence could lead to activation of cancer immunogenicity." (PMID 28765607, 2017). "Importantly, DHX9 is currently being explored as a target for cancer therapy." (PMID 28765607, 2017). "It stabilizes pro-tumorigenic KYNU protein, promotes cancer stemness via WNT/β-catenin signaling, inhibits ferroptosis through the miR-335-5p/GPX4 axis, and modulates innate immunity via DHX9 interaction." (PMID 40852728, 2025). "This trend was consistent in another cancer cell line, U2OS, underscoring the critical role of DHX9 SUMOylation in cell survival." (PMID 39019926, 2024). "The cellular functions of DHX9 remain enigmatic, but it is involved in epithelial-mesenchymal transition (EMT) in cancer biology and has been shown to function as an antiviral factor." (PMID 38193690, 2024). "Knockdown of DHX9 significantly enhances MYXV replication and progeny virus production in cancer cells, where viral replication is restricted." (PMID 37377603, 2023). "We recently reported that DHX9/RHA forms unique antiviral granules in the cytoplasm, which restrict MYXV replication in human cancer cells by reducing viral late protein synthesis and progeny virus formation." (PMID 37377603, 2023). "Therefore, DHX9 may be a new target for the treatment of malignant tumors." (PMID 37214432, 2023). "We found that AS-tDR-007333 precipitated with several cancer-related RNA-binding proteins, including HSPB1, DHX9, ACTB, YBX3, and ILF2." (PMID 35526007, 2022). "Significantly upregulated PRGs included PYCARD in 12 cancers; GSDMB in 10 cancers; IL18 in 9 cancers; GSDMD, CASP8, GZMB, and GPX4 in 8 cancers; AIM2 and CASP6 in 7 cancers; GZMA in 6 cancers; GSDME, CASP4 and DHX9 in 5 cancers; GSDMA and GSDMC in 4 cancers." (PMID 36605187, 2022). "GSDMC, GSDMD, GSDME, ZBP1, AIM2, DHX9 and NLRP3 demonstrated significant amplification across cancers." (PMID 36605187, 2022). "A majorly pan-cancer positive correlation between promotor methylation and gene expression of GSDMA, CASP1, NLRP9, GZMB, DHX9, DDX3X, SFRS2IP (CASP11) and GPX4 was observed." (PMID 36605187, 2022). "In LIHC, DHX9, DHX32, and DHX15 play important roles in promoting cancer cell motility and proliferation, inhibiting cell apoptosis, and indicating a poor prognosis." (PMID 35814441, 2022).